WDR62 (WD repeat domain 62)
Description:
Required for cerebral cortical development. Plays a role in neuronal proliferation and migration. Plays a role in mother-centriole-dependent centriole duplication; the function also seems to involve CEP152, CDK5RAP2 and CEP63 through a stepwise assembled complex at the centrosome that recruits CDK2 required for centriole duplication.
Synonyms: C19orf14; DKFZP434J046; FLJ33298; MCPH2
Tractability: PROTAC: ubiquitination databases record sites on it.
Gene: Protein-coding gene on chromosome 19 (36,054,649 to 36,105,108, forward strand). Ensembl gene ENSG00000075702.
Subcellular location: Nucleus; Cytoplasm, cytoskeleton, spindle pole; Cytoplasm, cytoskeleton, microtubule organizing center, centrosome; Cytoplasm, cytoskeleton, microtubule organizing center, centrosome, centriole
Subcellular location (Human Protein Atlas): Cytosol; Centriolar satellite
Gene Ontology:
Molecular function: protein binding
Biological process: centriole replication; cerebral cortex development; mitotic spindle organization; neurogenesis; regulation of centrosome cycle; positive regulation of neuroblast proliferation; positive regulation of neuron migration; regulation of neuron differentiation
Cellular component: centriolar satellite; centrosome; nucleus; spindle pole; centriole
Genetic constraint (gnomAD): Loss-of-function variants: 113 observed, 163.99 expected, observed/expected ratio (o/e) 0.69, 90% interval 0.59 to 0.81. The upper end of that interval is the gene's LOEUF score, 0.81, which puts it in group 3 of 6, group 1 being the genes least tolerant of losing a copy. Missense variants: 1,819 observed, 2,037.4 expected, observed/expected ratio (o/e) 0.89, 90% interval 0.86 to 0.93. Synonymous variants: 792 observed, 834.21 expected, observed/expected ratio (o/e) 0.95, 90% interval 0.89 to 1.01.
Gene-disease validity (ClinGen):
ClinGen rates the evidence that WDR62 causes each of these diseases.
microcephaly 2, primary, autosomal recessive, with or without cortical malformations (autosomal recessive): Definitive.
Homologues: Orthologues: chimpanzee WDR62 (99% identical), macaque WDR62 (97% identical), dog WDR62 (83% identical), pig WDR62 (82% identical), rabbit WDR62 (81% identical), rat Wdr62 (78% identical), mouse Wdr62 (77% identical), guinea pig WDR62 (76% identical), tropical clawed frog wdr62 (42% identical). Paralogues in human: MAPKBP1 (39% identical), WDR7 (11% identical), TEP1 (10% identical), WDR81 (10% identical), AHI1 (8% identical), NEDD1 (8% identical), WDR75 (8% identical), WDR17 (8% identical), NWD1 (7% identical), WDR27 (6% identical), WDR88 (6% identical), PAFAH1B1 (6% identical), and 14 more.
Diseases named in the same sentence as WDR62 in open-access papers:
WDR62 is named in the same sentence as 71 diseases in open-access papers, as found by Europe PMC text mining. Sharing a sentence is not in itself a finding about the gene and the disease. The quoted sentences say what the papers report.
microcephaly (66 papers, 2011 to 2026). A congenital or acquired developmental disorder in which the circumference of the head is smaller than normal for the person's age and sex. "Loss of Wdr62 in murine models results in microcephaly due to depletion of neural progenitor cells, arising from spindle defects and mitotic arrest caused by impaired interaction with Aurora A, ultimately triggering apoptosis of progenitor cells." (PMID 41555927, 2025). "That WDR62 mutations are associated with microencephaly is an interesting tie in with mutations in Akt3 in MPPH syndrome." (PMID 40048438, 2025). "It has recently been shown that WDR62 associates with Aurora B, is closely associated with the chromosome passenger complex, and mutations in WDR62 are associated with microencephaly." (PMID 40048438, 2025). "Whole-genome sequencing of 32 Chinese parent-offspring trios with ASD showed several microcephaly-associated genes, which included WDR62 with rare de novo mutations." (PMID 36571716, 2023). "Previous studies showed that knock-down of ASPM and Wdr62, two genes implicated in microcephaly that encode mitotic spindle and centrosome proteins, also induced shortening of astral MTs in human cell lines, resulting in spindle mis-orientation." (PMID 33742057, 2021). "In all patients with mutations in the WDR62 gene, microcephaly was observed in the neonatal period, gradually worsening in the childhood period." (PMID 33921653, 2021). "A recent large-scale whole-genome sequencing study found numerous microcephaly-related gene mutations in patients with autism spectrum disorder, including WDR62, ASPM and ZNF335." (PMID 33937237, 2021). "In contrast, patients harboring mutations in WDR62, which is second most frequently mutated in primary microcephaly, have presented with simplified hippocampal gyration and dysmorphology as part of a broad spectrum of structural malformations." (PMID 33042990, 2020). "In the fish model, for example, homozygous mutations in both aspm and wdr62 are necessary to produce the microcephaly phenotype." (PMID 33178111, 2020). "During human embryonic development, WDR62 functions in neural progenitor populations are particularly critical as inherited mutations on WDR62 cause primary microcephaly." (PMID 33042990, 2020). "Previous studies have identified numerous (>35) patient mutations in WDR62 that are causative of primary microcephaly." (PMID 33042990, 2020). "We have identified a novel compound heterozygous c.797C>T in exon 7 and c.1102G>A mutations in exon 9 of the WDR62 gene in two affected siblings of Saudi family with intellectual disability, speech impediments walking difficulty and primary microcephaly." (PMID 31258591, 2019). "To model human microcephaly, we developed cerebral organoids from WDR62-deficient human pluripotent stem cells (hPSCs)." (PMID 31197141, 2019). "To model WDR62 mutation-associated human microcephaly, we adopted a cerebral organoid culture system." (PMID 31197141, 2019). "The cilium and microcephaly phenotypes arising from WDR62 mutations resemble those from mutations in other genes associated with MCPH and Seckel syndrome." (PMID 31197141, 2019). "More than 50% of MCPH cases worldwide are caused by mutations in either abnormal spindle-like microcephaly-associated (ASPM) or WDR62." (PMID 30566428, 2018). "Recessive mutations in WD repeat domain 62 (WDR62) cause microcephaly and a wide spectrum of severe brain malformations." (PMID 28272472, 2017). "Mutations or loss of Wdr62 expression therefore leads to mitotic delay and death of neural progenitor cells, thereby resulting in microcephaly." (PMID 29209173, 2017). "Most genes linked to decreased brain size encode centrosomal proteins (e.g. WDR62) and dysfunction of the mitotic spindle is a well-established cause of microcephaly." (PMID 26070982, 2015).
microcephaly (continued). "A previous study revealed five homozygous WDR62 mutations, including deletions and premature terminations, in patients of Turkish origin suffering from severe brain malformations and microcephaly." (PMID 25951892, 2015). "We next examined the WES data using a second approach to identify all rare variants in genes known to be associated with epilepsy and microcephaly (see Method 2); the same mutation in WDR62 was identified as the only candidate." (PMID 24479948, 2014). "WES identified ten exome-wide homozygous variants including a rare variant in WDR62, encoding a protein essential to cerebral cortex development and known to cause microcephaly and thus felt to be a strong candidate gene for the disorder in this family." (PMID 24479948, 2014). "Some recent studies have also documented a critical role of WDR62 in the proliferation of neuronal precursors, and that mutation of the WDR62 gene will induce microcephaly and dysplasia of human brain." (PMID 23898938, 2013). "It is likely that the deceased sister of the index patient who also had severe microcephaly at birth and intellectual disability, carried the p.R438H / p.D955Afs*112 mutations of the WDR62 gene." (PMID 24228726, 2013). "Previously the locus was reported in Pakistani families only but the mutations in WDR62 gene have been found in microcephaly patients from other countries as well." (PMID 21668957, 2011). "This study was initiated to screen WDR62 mutations in four consanguineous Pakistani families with autosomal recessive primary microcephaly." (PMID 21961505, 2011). "Notably, microcephaly-associated WDR62 mutations disrupt interaction with BAG2 and fail to restore HPRT levels." (PMID 41787126, 2026). "However, molecular mechanisms for microcephaly mutations in centrosomal proteins, such as Cep135, Cep152, and WDR62, remain clouded." (PMID 38857398, 2024). "However, the identification of various mutations in WDR62 splice sites associated with microcephaly or intellectual disability in the HGMD database suggests new therapeutic possibilities." (PMID 38576530, 2024). "In addition to these two models, perturbation in the migration of neurons and glial cells has also been suggested as the cause of primary microcephaly in patients carrying mutations in WDR62." (PMID 36831309, 2023). "In the same way, in WDR62/Wdr62 mutant cerebral organoids and a KO mouse model, during cortical development progenitors exhibit cilium disassembly defects associated with decreased proliferation and increased differentiation contributing to microcephaly." (PMID 36139475, 2022). "However, in both cases PC are defective, leading to a microcephaly phenotype, strongly suggesting that loss of function of Wdr62 is important for the aRG pool." (PMID 36139475, 2022). "Considering that all patients enrolled in our study only had CHD, whether our WDR62 variants are associated with microcephaly and reproductive disorders should be clarified in further research." (PMID 35808830, 2022). "Mutations in WDR62 are associated with microcephaly in humans." (PMID 34326322, 2021). "It has been hypothesised that the loss of WDR62 can exhaust the pool of neuroprogenitor cells required for neurogenesis, leading to thinning of the forebrain cortex and hence microcephaly." (PMID 34059773, 2021). "We also examined the expression of other microcephaly-related genes: Mcph1, Cdk5rap2, and Aspm that were involved in germ cell maintenance, but we did not detect significant differences in their mRNA expression with WDR62 deficiency." (PMID 34059773, 2021). "Others have shown that mutations in the human WDR62 resulted in microcephaly and a wide spectrum of cortical abnormalities, while a loss in the WDR62 protein function in mice causes mitotic delay, the death of neuron progenitor cells, reduced brain size and dwarfism." (PMID 32498399, 2020). "Based on the referral note for this patient, mutations in WDR62 could be of relevance for the reported microcephaly." (PMID 31258591, 2019).
microcephaly (continued). "Mutations in the WDR62 gene are also frequently identified in patients with microcephaly." (PMID 32038172, 2019). "Strikingly, most mouse models of microcephaly where the candidate genes (CDK5RAP2, CPAP, ASPM, Wdr62, and Plk4) were either completely ablated or highly overexpressed have invariably displayed apoptosis as a prominent mechanism for causing NPCs depletion and microcephaly." (PMID 32457578, 2020). "A central molecular mechanism for microcephaly in MCPH2 may be a deficiency or dysfunction of WDR62 at the spindle pole of dividing cells due to processes such as non-expression, loss of essential spindle targeting domains, misfolding or rapid degradation of the mutant protein." (PMID 24228726, 2013). "Therefore, mutated wdr62 may results in depletion of progenitor pool affecting the proliferation rate and thus produce reduced neuron numbers causing primary microcephaly." (PMID 21961505, 2011). "In this study, we investigated four consanguineous families with congenital microcephaly and identified three novel variants in CPAP, WDR62, and ASPM." (PMID 41555927, 2025). "This study identifies novel variants in CPAP, WDR62, and ASPM and further delineates the mutational landscape of microcephaly-associated genes in the Pakistani population." (PMID 41555927, 2025). "According to GO analysis, these genes are associated with either abnormal hematopoiesis (Aurkb, Fen1, Hrob, Kif20a, Rad51ap1 and Tsr2) or microcephaly (Casc5, Hmgb3, Ncaph and Wdr62), or both (Fanca and Trip13)." (PMID 37661832, 2023). "All common mutations causing microcephaly are present in genes implicated in cell division (MCPH1, ASPM, CDK5RAP2, CENPJ, STIL, WDR62, and CEP152)." (PMID 37294214, 2023). "Our findings provide a new perspective on the relationship between the microcephaly gene WDR62 and ASD etiology that will benefit clinical diagnosis and intervention of ASD." (PMID 36571716, 2023). "Infratentorial anomalies such as cerebellar hypoplasia, with or without an enlarged posterior fossa, have been described, especially in ASPM-, CDK5RAP2-, and WDR62-related microcephaly." (PMID 35456440, 2022). "Analysis of gross external morphology revealed that over 80% Wdr62‐null mice exhibited a range of abnormalities including developmental retardation, coloboma or microphthalmia, microcephaly, and infertility." (PMID 35808830, 2022). "WDR62 has been reported to be engaged in microcephaly, reproductive system diseases, and cancer in humans." (PMID 35808830, 2022). "The second most common cause of primary microcephaly are mutations in WDR62 (WD repeat domain 62, also known as MCPH2), a scaffold protein associated with the spindle pole." (PMID 35069108, 2021). "Depletion of Wdr62 in mice lead to microcephaly due to reduced proliferation of neural progenitors, spindle instability and abnormalities in centrosome inheritance." (PMID 35069108, 2021). "Mutations in the MCPH2 gene, WD40-repeat protein 62 (WDR62), are causative of primary microcephaly and cortical malformations in humans." (PMID 33042990, 2020). "MCPH2 (WDR62), the next most common gene causative of microcephaly, showed cell cycle-dependent expression and functions in centriole biogenesis and mitotic spindle orientation." (PMID 32121580, 2020). "Here, authors demonstrate that WDR62 depletion leads to neural precursor cell depletion and microcephaly via WDR62-CEP170-KIF2A pathway that promotes cilium disassembly." (PMID 31197141, 2019). "Although these mouse models are slightly different in their generation and focus on different aspects of Wdr62 biology, they all exhibit similar and subtle microcephaly phenotypes due to the NPC disruption." (PMID 31197141, 2019). "Future studies should determine to what extent disruption of individual WDR62 functions contribute to microcephaly." (PMID 31197141, 2019).
microcephaly (continued). "Several genes that encode for proteins implicated in centrosome function and spindle orientation are mutated in microcephaly in humans: MCPH5 or ASPM (abnormal spindle-like microcephaly associated), WDR62/MCPH2, and CEP63." (PMID 30687396, 2018). "As in humans, disruption of WDR62 in mouse and Drosophila leads to microcephaly, highlighting its evolutionarily conserved function." (PMID 28272472, 2017). "Tcf4 binds together with microcephaly-associated transcription factors Smad4, Sox2, Chd7 and Ep300 to active enhancers at primary microcephaly genes Mcph1 and Wdr62." (PMID 28375211, 2017). "The results of our phylogenetic comparative analyses provide direct evidence that evolution of brain size is indeed linked to four microcephaly genes (ASPM, CDKRAP2, STIL, WDR62) in two mammalian clades, Glires and Euungulata." (PMID 24898820, 2014). "Both WDR62 and CENPJ appear to be rare causes of severe congenital microcephaly reported in few pedigrees." (PMID 23704059, 2013). "Although there were no imaging studies presented in the previous mapping of this locus, recent findings by different groups suggest that WDR62 is the MCPH2 gene and have extended the phenotype beyond ordinary microcephaly." (PMID 21668957, 2011). "Because de novo mutation of Wdr62 has been found in ASD patients and ~15% of ASD patients have microcephaly, we went on to inspect whether Wdr62-KO mice display autistic behaviors." (PMID 36571716, 2023). "Correspondingly, the Wdr62‐null mice also showed microcephaly and all were infertile." (PMID 35808830, 2022). "Interestingly, complete ablation of Wdr62 also led to mild microcephaly, in contrast to the drastic reduction of mutant organoid sizes." (PMID 31197141, 2019). "Wdr62 mutant mice exhibit a mild microcephaly phenotype, suggesting that certain aspects of human WDR62 biology may not be adequately modeled in mice." (PMID 31197141, 2019). "This indicates that Wdr62 cKO-induced microcephaly can be rescued by increased JNK1 activity." (PMID 30566428, 2018). "Other noteworthy predictions are for variants in WDR62, which result in microcephaly with or without cortical malformations in an autosomal recessive manner." (PMID 28977528, 2017). "However, human NDE1-associated microcephaly is much more severe than the forms of the disorder involving mitotic spindle assembly genes, such as ASPM and WDR62 (refs 4, 5)." (PMID 27553190, 2016). "We hypothesize that microcephaly-associated mutation of CEP90 causes defective centriole duplication, similar to depletion of CEP90 or of MCPH proteins such as CDK5RAP2, CEP152, WDR62 or CEP63." (PMID 26297806, 2015). "Many genes have been implicated in the development of microcephaly (summarized inTable 1) includingASPM,MCPH1,CDK5RAP2,CEP152,CENPJ,WDR62,STIL,CASC5,CEP135,ZNF335,PHC1,CDK6, with many of them contributing to centrosome and spindle protein dysfunction during mitosis." (PMID 26535115, 2015). "This study supports the notion that WDR62 mutations results in brain malformations in addition to primary microcephaly irrespective of family origin and ethnicity." (PMID 21961505, 2011). "Furthermore it also indicates that beside ASPM, WDR62 gene is a relevant contributor for autosomal recessive primary microcephaly in Pakistan, being responsible for about 4% cases." (PMID 21961505, 2011). "Interestingly, tri-allelism (knockout of two mutant copies of one gene and only one mutant copy of another gene), Wdr62 (+/−), and Aspm (−/−), in mice embryos show comparatively severe cellular defects, and thus microcephaly, showing predominant effects on late neurogenesis." (PMID 36831309, 2023). "Furthermore, microcephaly, growth retardation, microphthalmia, and embryonic lethality observed in our Wdr62‐null mice were largely consistent with another homozygous Wdr62 mutant model (WDR62stop/stop), which were also constructed with CRISPR/Cas9 editing technology." (PMID 35808830, 2022).